KCNJ10 (potassium inwardly rectifying channel subfamily J member 10)
Description:
May be responsible for potassium buffering action of glial cells in the brain (By similarity). Inward rectifier potassium channels are characterized by a greater tendency to allow potassium to flow into the cell rather than out of it. Their voltage dependence is regulated by the concentration of extracellular potassium; as external potassium is raised, the voltage range of the channel opening shifts to more positive voltages. The inward rectification is mainly due to the blockage of outward current by internal magnesium. Can be blocked by extracellular barium and cesium. In the kidney, together with KCNJ16, mediates basolateral K(+) recycling in distal tubules; this process is critical for Na(+) reabsorption at the tubules.
Synonyms: Kir4.1; Kir1.2; BIRK-10; KCNJ13-PEN; SESAME
Tractability: Small molecule: it belongs to a druggable protein family. Antibody: UniProt places it where antibodies can reach, with high confidence; its Gene Ontology location is reachable by antibodies, with high confidence; UniProt predicts a signal peptide or a membrane-spanning region. PROTAC: ubiquitination databases record sites on it.
Target class: Inwardly rectifying potassium channel; Potassium channels; Voltage-gated ion channel; Ion channel
Gene: Protein-coding gene on chromosome 1 (159,998,651 to 160,070,483, reverse strand). Ensembl gene ENSG00000177807.
Subcellular location: Membrane; Basolateral cell membrane
Pathways (Reactome):
Neuronal System: Activation of G protein gated Potassium channels; Inhibition of voltage gated Ca2+ channels via Gbeta/gamma subunits; Potassium transport channels
Gene Ontology:
Molecular function: inward rectifier potassium channel activity; protein binding; ATP-activated inward rectifier potassium channel activity; potassium channel activity
Biological process: potassium ion transmembrane transport; potassium ion import across plasma membrane; potassium ion transport; cellular response to potassium ion; non-motile cilium assembly
Cellular component: basolateral plasma membrane; membrane; astrocyte projection; cell body; plasma membrane; ciliary base
Genetic constraint (gnomAD): Loss-of-function variants: 9 observed, 23.23 expected, observed/expected ratio (o/e) 0.39, 90% interval 0.23 to 0.68. The upper end of that interval is the gene's LOEUF score, 0.68, which puts it in group 2 of 6, group 1 being the genes least tolerant of losing a copy. Missense variants: 337 observed, 503.72 expected, observed/expected ratio (o/e) 0.67, 90% interval 0.61 to 0.73. Synonymous variants: 184 observed, 197.54 expected, observed/expected ratio (o/e) 0.93, 90% interval 0.82 to 1.05.
Gene-disease validity (ClinGen):
ClinGen rates the evidence that KCNJ10 causes each of these diseases.
EAST syndrome (autosomal recessive): Definitive. SeSAME syndrome is characterized by seizures, sensorineural deafness, ataxia, intellectual deficit, and electrolyte imbalance (hypokalemia, metabolic alkalosis, and hypomagnesemia).
enlarged vestibular aqueduct syndrome (autosomal dominant): Disputed.
Homologues: Orthologues: macaque KCNJ10 (100% identical), pig KCNJ10 (99% identical), mouse Kcnj10 (99% identical), guinea pig KCNJ10 (99% identical), rabbit KCNJ10 (99% identical), dog KCNJ10 (98% identical), rat Kcnj10 (98% identical), tropical clawed frog kcnj10 (83% identical), zebrafish kcnj10a (72% identical), zebrafish kcnj10b (67% identical), Drosophila melanogaster Irk1 (38% identical), Caenorhabditis elegans irk-2 (36% identical), and 4 more. Paralogues in human: KCNJ15 (59% identical), KCNJ1 (46% identical), KCNJ12 (39% identical), KCNJ18 (39% identical), KCNJ13 (38% identical), KCNJ2 (38% identical), KCNJ14 (37% identical), KCNJ4 (37% identical), KCNJ3 (37% identical), KCNJ6 (36% identical), KCNJ9 (36% identical), KCNJ11 (36% identical), and 3 more.
Diseases named in the same sentence as KCNJ10 in open-access papers:
KCNJ10 is named in the same sentence as 152 diseases in open-access papers, as found by Europe PMC text mining. Sharing a sentence is not in itself a finding about the gene and the disease. The quoted sentences say what the papers report.
epilepsy (85 papers, 2008 to 2025). A brain disorder characterized by episodes of abnormally increased neuronal discharge resulting in transient episodes of sensory or motor neurological dysfunction, or psychic dysfunction. "The incidence of epilepsy is slightly higher in men than in women, and according to our results, gender and the KCNJ10 variant were correlated." (PMID 40142207, 2025). "According to our results, rs61822012 and rs1186685 KCNJ10 were associated with epilepsy (p-value = 0.048 and 0.04), respectively." (PMID 40142207, 2025). "The variant genotype A/A of rs946420 in the KCNJ10 gene can also be designated as a protective factor against epilepsy (p-value = 0.045)." (PMID 40142207, 2025). "Based on our results, we infer that both rs61822012 and rs1186685 KCNJ10 are involved in the risk of epilepsy." (PMID 40142207, 2025). "The SOX2-bound genes that are associated with glutamate import and epilepsy were identified as Kcnj10 (Kir4.1), Slc1a2 (GLT-1), and Slc1a3 (GLAST)." (PMID 36543123, 2022). "Loss-of-function mutations in the KCNJ10 gene have been found to elicit “EAST” (epilepsy, ataxia, sensorineural deafness, and tubulopathy) or “SeSAME” (seizures, sensorineural deafness, ataxia, mental retardation, and electrolyte imbalance) syndrome." (PMID 34638578, 2021). "Mutations in certain ion channel genes important for SCN function, such as SCN1A and KCNJ10, are well-known to strongly associate with epilepsy phenotypes in humans, and have served for many years as leads for AED development without great success." (PMID 32714261, 2020). "Mutations and common variants of KCNJ10, the gene encoding the inward-rectifying potassium channel Kir4.1, are associated with rare and common forms of epilepsy, respectively." (PMID 32714261, 2020). "Studies documenting the important role of Kir4.1 in the retina and altered retinal function in epilepsy patients with KCNJ10 mutations suggest a potential mechanistic link between circadian rhythms and epilepsy that deserves further examination." (PMID 32714261, 2020). "Human Kir4.1 potassium channels (KCNJ10) have been implicated in maintaining K+ homeostasis, with mutations in the loci causing epilepsy." (PMID 31025939, 2019). "Nevertheless, glial expression of another voltage gated potassium channel that is associated with human epilepsy, KCNJ10, has been shown to lead to epileptic activity in a mouse model, possibly via its role in buffering extracellular potassium and glutamate." (PMID 31393878, 2019). "Mutations in KCNJ10 have been linked to developmental disorders characterized by early onset seizures, ataxia, epilepsy, and profound developmental delay." (PMID 29464197, 2018). "KCNJ10 associations are also observed in individuals with epilepsy, indicating that similar epilepsy mechanisms are shared between rodents and humans." (PMID 28620084, 2017). "We found that KCNJ10 variants were significantly associated with epileptic spasms (χ2 = 11.131, df = 2, p = 0.004), with a particularly good prognosis of the epilepsy outcome." (PMID 27677466, 2016). "Among Kir4 channels, the Kir4.1, encoded by the KCNJ10 gene, is the only one that has been associated to epilepsy." (PMID 27064559, 2016). "Dysfunction of the inwardly-rectifying potassium channels Kir4.1 (KCNJ10) represents a pathogenic mechanism contributing to Autism-Epilepsy comorbidity." (PMID 27677466, 2016). "Our results confirm that variants in KCNJ10 deserve attention in autism-epilepsy, and provide insight into the molecular mechanisms of autism and seizures." (PMID 27677466, 2016). "In line with the pathophysiological relationship between the Kir4.1 channel impairment and both epilepsy and developmental disorders, we investigated the frequency of KCNJ10 mutations in several children with cryptogenic epilepsy and autism spectrum traits." (PMID 25784856, 2015). "The mutations of KCNJ10 cause specific disorders, consisting of epilepsy, ataxia, sensorineural deafness, and tubulopathy." (PMID 25874548, 2015).
epilepsy (continued). "Although it is formally possible that the KCNJ2 mutation in cis with KCNJ10 contributes separately to SQT3S or autism–epilepsy pathogenesis, each playing a clear distinctive role, this conclusion appears to be too simplistic." (PMID 24794859, 2014). "Human polymorphisms in KCNJ10, the gene that encodes Kir4.1, are associated with epilepsy and a glial specific deletion of Kir4.1 in mice reduces K+ clearance from the synaptic cleft." (PMID 23882181, 2013). "To date, we have identified several new probands displaying an autism–epilepsy phenotype who carry mutations in KCNJ10 that cause gain-of-function effects, assessed by using astrocytoma cell lines." (PMID 24062639, 2013). "The K+ channel expressed by the KCNJ10 gene (Kir4.1) has previously been recognized as pathogenic in man, causing a constellation of symptoms, including epilepsy, ataxia, sensorineural deafness and a renal tubulopathy (EAST syndrome)." (PMID 23077521, 2012). "We also that the A/A variant genotype of rs2820585 in KCNJ10 may confer a reduced risk of epilepsy, as well as the A/A genotype of rs946420 in KCNJ10." (PMID 40142207, 2025). "In addition, regarding the KCNJ10 gene, we found that rs2820585, rs946420, rs1186679, rs61822012, and rs1186685 were significantly correlated with epilepsy risk (p-values = 0.034, 0.045, 0.021, 0.048, and 0.018), respectively." (PMID 40142207, 2025). "Finally, loss-of-function mutations in the KCNJ10 gene encoding Kir4.1 cause the epileptic disorders known as “EAST” (epilepsy, ataxia, sensorineural deafness, and tubulopathy)." (PMID 36428502, 2022). "Mutations in the human KCNJ10 gene encoding Kir4.1 were reported to cause the epileptic disorders known as “EAST” (Epilepsy, Ataxia, Sensorineural deafness and Tubulopathy) and “SeSAME” (Seizures, Sensorineural deafness, Ataxia, Mental retardation, and Electrolyte imbalance) syndrome (OMIM 612780)." (PMID 33424762, 2020). "Based on our data, mutations in Kcnj10 segregating in the HMDP are associated with initial seizure effects that diminish over time, which may also be true in humans with epilepsy, raising the question of the nature of the association of Kcnj10 with epilepsy." (PMID 28620084, 2017). "However, Kir4.1-/- mice display an epileptic phenotype and missense mutations in KCNJ10, the gene encoding Kir4.1, have been associated with epilepsy in humans." (PMID 25826753, 2015). "Studies about the relationship between KCNJ10 polymorphisms and epilepsy were inconsistent." (PMID 25874548, 2015). "SeSAME (seizures, sensorineural deafness, ataxia, mental retardation, and electrolyte imbalance) or EAST (epilepsy, ataxia, sensorineural deafness, and tubulopathy) syndrome is caused by mutations of the K (+) channel KCNJ10 (Kir4.1) gene, which is an autosomal recessive disease." (PMID 25140267, 2014). "Humans KCNJ10 mutations are also associated to seizure susceptibility, idiopathic generalized epilepsy or to complex syndromes that encompass epilepsy." (PMID 22807916, 2012). "The important role of the Kir4.1 channels is demonstrated by a number of studies identifying mutations in the Kir4.1 gene (KCNJ10) as a reason for symptoms found in the EAST syndrome (epilepsy, ataxia, sensorineural deafness, and tubulopathy)." (PMID 21283711, 2011). "In addition KCNJ10 has also been considered as a ‘susceptibility gene’ for epilepsy in humans." (PMID 23965030, 2013). "In humans, mutations in KCNJ10 (Kir4.1) are responsible for EAST syndrome (also known as SeSAME syndrome), characterized by epilepsy, ataxia, sensorineural deafness, and salt-wasting tubulopathy." (PMID 40358700, 2025). "This study highlights a potential link between voltage-gated potassium channels and the risk of epilepsy, especially concerning the genetic variations in the KCNAB1 and KCNJ10 genes." (PMID 40142207, 2025). "KCNJ10 mutation was also reported in five Saudi patients from two families who presented with EAST syndrome, epilepsy, ataxia, and sensorineural deafness." (PMID 37628333, 2023).
epilepsy (continued). "Regarding the other potassium inward rectifier channel KCNJ10, patients suffering from KCNJ10 mutations develop EAST syndrome, which is characterized by epilepsy, ataxia, sensorineural deafness, and renal tubulopathy." (PMID 35005553, 2022). "Mutations in KCNJ10 (potassium channel, inwardly rectifying subfamily J member 10), which encodes a potassium channel, cause EAST (epilepsy, ataxia, sensorineural deafness and tubulopathy) syndrome (also called SeSAME syndrome)." (PMID 33917666, 2021). "This syndrome characterised by Epilepsy, Ataxia, Sensorineural deafness, and Tubulopathy resulting from a mutation of the KCNJ10 gene coding for Kir4.1, an inward rectifying potassium channels in the brain, inner ear and kidney." (PMID 34117382, 2021). "It has been shown that the hypofunction of Kir4.1 channels in astrocytes was involved in various epileptic disorders including not only epilepsy models in animals, but also EAST/SeSAME syndrome with KCNJ10 mutations and TLE in humans." (PMID 30813600, 2019). "This syndrome, characterized by epilepsy, ataxia, sensorineural deafness and tubulopathy (referred to as EAST syndrome), is a rare recessive genetic disease affecting the K+ channel Kir4.1 encoded by KCNJ10." (PMID 27234911, 2017). "In humans, KCNJ10 loss-of-function mutations segregate with the EAST or SeSAME syndrome, a rare autosomic recessive disorder characterized by epilepsy, ataxia, sensorineural deafness, and tubulopathy." (PMID 25784856, 2015). "Recently, we reported a previously unrecognized symptom constellation comprising epilepsy, ataxia, sensorineural deafness, and tubulopathy (EAST syndrome) associated with recessive mutations in the KCNJ10 gene." (PMID 23924083, 2013). "Because of the suggested role of KCNJ10 in both epilepsy and PDS/EVA, we also screened 3 unrelated patients with the combination of Pendred syndrome and seizures." (PMID 23965030, 2013). "KCNJ10, expressed in glial cells, helps to buffer extracellular potassium and thus modulates neuronal excitability explaining epilepsy in this autosomal recessive disorder." (PMID 24244558, 2013). "Mutations in the human Kir4.1 gene, KCNJ10, are associated with epilepsy and a compromised glial potassium spatial buffering has been suggested to underlie the epilepsy phenotype." (PMID 23270518, 2012). "KCNJ10 and KCNJ9 have also been correlated with the risk of epilepsy." (PMID 40142207, 2025). "A role for Kir5.1 in epilepsy and/or seizure disorders has not been previously addressed, despite the strong evidence linking the related protein, Kir4.1 (encoded by Kcnj10), to seizure disorders." (PMID 33232300, 2021). "In a more recent study, co-injection of the kcnj10a morpholino with mRNA from patients with KCNJ10 mutations related to autism spectrum disorder and epilepsy did not rescue the phenotype, while normal human KCNJ10 mRNA did." (PMID 33917666, 2021). "However subsequent work by others has shown that recessive mutations in KCNJ10 do indeed cause hearing loss, but as part of a complex syndrome, EAST syndrome, consisting of Epilepsy, Ataxia, Sensorineural deafness and renal Tubulopathy." (PMID 23965030, 2013). "Co-occurrence of epilepsy and ASD in patients harboring KCNJ10 gain-of-function mutations suggests that dysfunction in the astrocytic-dependent K+ buffering may be a common mechanism contributing to seizures as well as the core behavioral features of ASD." (PMID 24062639, 2013). "To deal with this aspect of the Kir4.1 metabolism, we can hypothesize the presence of conditions seen already in other Kir4.1-related conditions such as epilepsy, which is often seen in comorbidity with depression, where it has been documented either loss or gain of function KCNJ10 variants." (PMID 34685608, 2021).
epilepsy (continued). "Mutations in the Kir4.1 gene (KCNJ10) cause the autosomal recessive disorder SeSAME/EAST Syndrome (seizures, sensorineural deafness, ataxia, mental retardation and electrolyte imbalance/epilepsy, ataxia, sensorineural deafness and tubulopathy) in human patients." (PMID 33348803, 2020). "In addition, polymorphisms in KCNJ10 are risk factors for epilepsy in humans, and seizures are a prominent component of the human disorder SeSAME/EAST syndrome, which results from loss-of-function mutations in KCNJ10." (PMID 29596047, 2018). "Variants of KCNJ10 have also been considered as a risk factor for seizure susceptibility in genetic association studies and biallelic mutations in KCNJ10 in humans are known to cause a syndromic form of hearing loss, EAST syndrome (epilepsy, ataxia, sensorineural deafness and renal tubulopathy)." (PMID 23965030, 2013). "It was found that a family history of epilepsy was influenced by KCNA1/rs2227910, KCNAB1/rs4679773, and KCNJ10/rs12122979 (p-values = 0.039, 0.011, 0.047)." (PMID 40142207, 2025). "In this study, we implied that KCNJ10 and KCNAB1 may mediate drug responsiveness in epilepsy patients." (PMID 40142207, 2025). "Furthermore, the time to remission was correlated with KCNJ10, and KCNV2 and KCNJ9 influenced the classification of epilepsy." (PMID 40142207, 2025). "With this in mind, we have collected a broader sample of ASD patients, with or without epilepsy, in order to screen KCNJ10 and perform genotype-phenotype correlations." (PMID 27677466, 2016). "A further indication for the involvement of AQP4 in epilepsy and for the proposed interplay between AQP4 and Kir4.1 comes from genetic studies showing that several SNPs in the KCNJ10 and AQP4 genes are associated with mTLE (Heuser and others 2010) (see also below)." (PMID 24609207, 2015).